CD47 (CD47 molecule)
Diseases named in the same sentence as CD47 in open-access papers (continued):
Sharing a sentence is not in itself a finding about the gene and the disease.
anemia (continued). "In contrast, since many cell types express CD47, therapy based on targeting that molecule could induce adverse effects and, in fact, treatment with anti-CD47 Abs induced the appearance of anemia in monkeys." (PMID 31921125, 2019). "Combined, these findings suggest a potential mechanism for anemia of chronic disease and that rhesus (Rh)-null individuals, who have <25% of normal CD47 levels, may be particularly vulnerable to anemia under inflammatory conditions and infections." (PMID 28077173, 2017). "Another cell event that links erythrocytic apoptosis and anemia is a change in CD47 expression." (PMID 28018860, 2016). "We speculated that the anemia observed in the single-dose pilot study was related to the known role of CD47 in the normal clearance of aging red blood cells." (PMID 26390038, 2015). "The initial anemia resolves as RBCs are replaced with younger cells and the age distribution of the red blood cell pool is shifted to younger cells that are presumably more resistant to the effects of CD47 blockade." (PMID 26390038, 2015). "In addition, studies in SIRPα-mutant mice, where the cytoplasmic signaling domain of the receptor is deleted, have shown a shorter half-life of normal CD47-expressing erythrocytes in these mice, which also present with mild anemia." (PMID 23401787, 2013). "However, the trials of anti-CD47, which were initially tested in hematological malignancies were discontinued due adverse effects of significant anemia, which may suggest off-target toxicity because CD47 is expressed on non-malignant blood cells." (PMID 37987252, 2023). "However, as CD47 is widely expressed on the surface of a broad range of cell types, including erythrocytes and platelets, a major limitation of CD47 blocking agents is the target-mediated drug disposition and the potential side effects, which include anaemia or thrombocytopenia." (PMID 37153563, 2023). "Additionally, given the widespread expression of CD47, anti‐CD47 may also lead to off‐target effects, and thus to side effects such as anemia." (PMID 37409429, 2023). "TTI-621 binds CD47 on a variety of hematologic cells and causes anemia in primates but exhibits minimal binding to human RBCs, presumably because it binds to CD47 in clusters in the cell membrane but not when it is distributed and associated with a cytoskeletal protein, spectrin, in human RBCs." (PMID 36293358, 2022). "However, single‐agent treatment with CD47‐SIRPα blocking therapeutics in patients is associated with a lack of therapeutic effect at the maximum tolerated dose (MTD) and significant dose‐limiting toxicity (DLT), most notably anaemia and thrombocytopenia." (PMID 35908284, 2022). "Thus, general targeting of CD47 by using antibody strategy is likely to induce important adverse events, such as phagocytic-induced severe anemia, thrombocytopenia and splenomegaly, as previously reported during non-clinical work, as well as in Phase I clinical trials." (PMID 34638503, 2021). "However, because ALX-148 is engineered based on the natural SIRPα allelic variant V1, it does not differentiate between CD47 expressed on tumor cells and RBCs, therefore anemia is still observed in clincial trials." (PMID 33790906, 2021). "However, anti-CD47 mAb therapies may increase the occurrence of transient anaemia, since red blood cells also express CD47." (PMID 34638388, 2021). "All these studies above suggest that antibody-trap like IMM0306 might be an ideal approach for CD47-targeted immunotherapy development since selective avoidance of RBCs mediated antigen-sink as well as anemia could be achieved along with the robust anti-tumor activity." (PMID 34305918, 2021). "Although CD47 has a major role in regulating phagocytosis, it is actually FcγR engagement that is requisite for phagocytosis; mice that are CD47-deficient have a largely normal phenotype, other than mild anemia or thrombocytopenia, without overt autoimmunity." (PMID 35582455, 2020).
anemia (continued). "Such spontaneous anemia is, however, not seen in CD47-deficient mice, suggesting that CD47 could also be needed on the macrophages to facilitate the clearance of erythrocytes in the spleen." (PMID 23401787, 2013). "Although we had hoped that human CD47 expression would protect mouse RBCs, these results suggest that any protective effect is insufficient to restore steady-state RBC levels or prevent anemia." (PMID 40956886, 2025). "CD47 is also widely expressed in normal human cells, especially on RBC, which leads to macrophages phagocytosis of RBC via ADCP, leading to anemia." (PMID 37510993, 2023). "Though previous studies have found anti-CD47 and anti-CD117 induced anemia to be mild and fully resolved within 2–3 weeks, further work will be needed to define the impact of neonatal anti-CD117 and anti-CD47 myeloablation on short and long-term anemia." (PMID 36615137, 2023). "Importantly, the intratumoral delivery of mCD47nb-Fc by the adenovirus vector did not cause severe anemia, thrombocytopenia, and other adverse events often seen with macrophage-mediated cellular phagocytosis after the systemic administration of anti-CD47 agents." (PMID 35837100, 2022). "Unexpectedly, engrafted mice also showed comparable RBC levels and anemia, regardless of CD47 humanization." (PMID 40956886, 2025). "Moreover, in this study, smokers with polycythemia and iron deficiency anemia were presented with lower CD47 levels compared to healthy nonsmokers which might also accelerate their apoptosis and the removal from the blood circulation by the splenic macrophages." (PMID 40587754, 2025). "However, as expected, anti-SIRPα treatment also exacerbated anemia during SAA by 14 dpst, consistent with the role of CD47 as an important “marker of self” on healthy cells, especially red blood cells." (PMID 38724533, 2024). "Previous studies have shown a high incidence of grade 3 and 4 treatment-related adverse events, including anemia, neutropenia, and thrombocytopenia, in patients with myelodysplastic syndromes (MDS) and acute myeloid leukemia (AML) with the CD47 antibody Hu5F9-G4 even at low doses." (PMID 38429732, 2024). "CD47 on non-immune cells such as red blood cells and platelets soak up CD47 blockers leading to anemia and thrombocytopenia." (PMID 37217603, 2023). "It was suggested that TTI-622 does not bind to RBCs, unlike many anti-CD47 agents, thereby limiting adverse events such as anemia." (PMID 35884427, 2022). "It is worth noting that the blockade of tumoral CD47 via a functional monoclonal antibody does not necessarily bring about hemagglutination, suggesting that anemia is not an unavoidable toxicity." (PMID 33790906, 2021). "AO-176 showed negligible binding to RBC and did not induce HA and transient anemia, comparing to other CD47 blocking antibodies." (PMID 34717705, 2021). "The most common adverse event (AE) of this humanized antibody is anemia due to its non-selective inhibition of CD47 on aging red cells." (PMID 32677994, 2020). "Thus, CD47 blockade has the potential to accelerate RBC clearance by unmasking of pro-phagocytic signals, leading to anemia when administered to patients." (PMID 32038992, 2019). "In contrast to the anti-CD47 mAb Hu5F9-G4 treatment-induced acute anemia in cynomolgus monkeys, none of the ADU-1805 doses affected the hemoglobin levels after single-dose administration." (PMID 31801627, 2019). "Anti-CD47 treatment also increased lymphocytic infiltration to the tumor site without unacceptable toxicity except short-term anemia observed immediately after dosing." (PMID 28100392, 2017). "In our study, we show that normal C57BL/6 mice treated with therapeutic doses of anti-mouse CD47-blocking antibody had no significant toxic effect except temporary anemia and white blood cells reduction." (PMID 28484448, 2017).
anemia (continued). "We further discuss implications for immunotherapy, noting that agents like magrolimab (anti-CD47) combined with azacitidine have demonstrated objective response rates (ORR) exceeding 80% in early-phase AML trials, though challenges such as on-target anemia persist." (PMID 41727472, 2026). "While CD47 humanization may have some effect, it was not sufficient to fully prevent the anemia observed at steady state in mice bearing high levels of human tissue macrophages, which are primarily supported by human M-CSF." (PMID 40956886, 2025). "Thus, anti-CD47 mAb can trigger antibody-dependent cellular cytotoxicity (ADCC) and phagocytosis (ADCP) towards normal cells in an Fc receptor-dependent manner, posing concerns for on-target adverse events such as anemia and thrombocytopenia." (PMID 36439116, 2022). "Thus, circumvention of anaemia or thrombocytopenia can be accomplished with various strategies, including the development of CD47 mAbs that bind to a distinct epitope that is not targetable on RBCs or by targeting SIRPα." (PMID 35908284, 2022). "Additionally, in a CLL-xenograft model developed in NOD/scid gamma mice, we demonstrate that the injection of CD47 agonist peptides reduces tumor burden without inducing anemia or toxicity in blood, liver, or kidney." (PMID 25734483, 2015). "However, phase 1 trials using monoclonal anti-CD47 antibodies were terminated due to insufficient activity (CC-90002, NCT02641002), life threatening side effects (Ti-061, 2016-004372-22; Hu5F9-g4, NCT02678338), or anemia (due to CD47 expression on red blood cells)." (PMID 33322769, 2020). "Magrolimab, a monoclonal antibody targeting CD47, demonstrated high response rates in phase Ib trials but was discontinued after the phase III ENHANCE-2 trial owing to lack of survival benefit and anemia-related toxicity." (PMID 40111422, 2025). "In contrast to CD47 antibodies, the recombinant human (rh)SIRPα‐based therapeutic TTI‐621 did not trigger anaemia in clinical studies." (PMID 35908284, 2022). "This could potentially be due to the design of the antibodies, as magrolimab also has specific toxicities such as RBC agglutination leading to anemia, a concern that was absent with SRF231 and other newer CD47 mAbs." (PMID 41484790, 2026).
melanoma (109 papers, 2004 to 2026). A malignant, usually aggressive tumor composed of atypical, neoplastic melanocytes. "CD47 exhibits a strong association with unfavorable prognosis in patients diagnosed with non-small-cell lung cancer, melanoma, and acute myeloid leukemia." (PMID 38532108, 2024). "In this report, we find that CD47 upregulation in melanoma occurs at the mRNA level and is associated with changes in chromatin accessibility at the CD47 promoter region using the assay for transposase-accessible chromatin with sequencing (ATAC-seq)." (PMID 39742254, 2024). "Transmembrane integrin-associated protein CD47 functions as a potent innate immunity checkpoint and is upregulated by many types of malignant cells, including melanoma during tumor progression." (PMID 39742254, 2024). "We previously established that high levels of CD47 protein on freshly isolated human tumor cells are associated with melanoma progression and immune evasion." (PMID 39742254, 2024). "Previous studies implicated protective functions of CD47 expressed by immune cells in the melanoma tumor microenvironment." (PMID 36768931, 2023). "The association of higher MCL1 with high CD47 and improved survival in melanomas suggests that this increased MCL1 is expressed by immune cells in the tumor microenvironment." (PMID 36768931, 2023). "Loss of CD47 in mice bearing B16 melanomas increased the abundance of TIGIT+ CD8 T cells and NK cells in the spleen while reducing CD8 T cell numbers and the percent of TIGIT+ CD8 T cells in tumors." (PMID 36768931, 2023). "In contrast, we found that elevated CD47 mRNA expression in human melanomas is associated with improved survival." (PMID 33925464, 2021). "The melanoma immune microenvironment in primary and metastatic sites can be influenced by CD47 expression, which is associated with melanoma metastasis via the inhibition of macrophages." (PMID 34367975, 2021). "More recently, two groups independently used syngeneic inactivated tumor cells deficient in CD47 as a vaccine in vivo to stimulate immune recognition of existing mouse melanoma or lymphoma." (PMID 35582455, 2020). "Genome editing experiments confirmed that loss of CD47 created only modest increases in melanoma phagocytosis." (PMID 31205227, 2020). "According to the result of our in vitro phagocytosis assay, melanoma cells resistant to vemurafenib were more susceptible to macrophage phagocytosis when CD47 was blocked." (PMID 29050218, 2017). "In support of the proposed model, melanoma cells resistant to vemurafenib appeared more susceptible to macrophage phagocytosis, suggesting that these cells are more critically dependent on CD47 for escaping the immune system." (PMID 29050218, 2017). "The functional significance of upregulation of CD47 by BRAF/MEK inhibitors is revealed by increased susceptibility of melanoma cells resistant to BRAF inhibitors to macrophage phagocytosis when CD47 is inhibited." (PMID 29050218, 2017). "We report here that treatment with BRAF or MEK inhibitors upregulates CD47 in melanoma cells in vitro and in vivo, and that melanoma cells resistant to BRAF inhibitors are more susceptible to macrophage phagocytosis upon CD47 blockade." (PMID 29050218, 2017). "Functional studies showed that melanoma cells resistant to vemurafenib were more susceptible to macrophage phagocytosis when CD47 was blocked." (PMID 29050218, 2017). "Additionally, CD47 expression in cancer cells, such as melanoma and colon cancer, has been linked to immune evasion mechanisms mediated by SIRPα signaling." (PMID 39160226, 2024). "Molecular mechanisms underlying upregulation of CD47 during melanoma progression remain largely unknown." (PMID 39742254, 2024). "Importantly, downregulation of NRF1 causes notable reduction of CD47 mRNA (>50%) and as a result, significant decrease in melanoma cell poolations with high CD47 levels." (PMID 39742254, 2024).
melanoma (continued). "Although loss or inhibitory of CD47 usually enhanced eliminating cancer cells, CD47 could positively and negatively regulate NK cell function in human melanomas, which may explain CD47 was associated with improved survival in melanomas." (PMID 35697717, 2022). "Similarly, treating wild-type mice with a CD47 antibody that blocks TSP1 binding delayed B16 melanoma growth, associating with increased NK cell recruitment and increased granzyme B and interferon-γ levels in intratumoral NK but not CD8+ T cells." (PMID 33925464, 2021). "In addition to “don’t eat me” signalling mediated by CD47, it was conceivable that susceptibility of melanoma cells to phagocytosis by macrophage was also influenced by altered “eat-me” signals transmitted by CRT." (PMID 29050218, 2017). "Moreover, we demonstrate that the constitutive expression of CD47 in melanoma cells is also associated with ERK signalling." (PMID 29050218, 2017). "Our results suggest that blunting of the immune-response may be associated with the increase in CD47 expression in melanoma cells." (PMID 29050218, 2017). "Furthermore, in melanoma, CD47 may protect NK cells from chronic inflammation, and CD47 deficiency resulted in splenic NK cell exhaustion." (PMID 35865547, 2022). "Here, Wootton and colleagues engineered NDV for targeted and localized CD47 blockade in murine melanoma and pancreatic ductal adenocarcinoma." (PMID 41322194, 2025). "CD47 is highly expressed across multiple tumor types, including melanoma, contributing to immune evasion." (PMID 41280655, 2025). "Investigating the blockade of CD47 in the B16-F10 melanoma model showed there was decreased CD47 expression relative to NDV alone presumably due to anti-CD47 and SIRPα-Fc binding of tumoral CD47 and receptor internalization or blockade of SIRPα binding." (PMID 41322194, 2025). "One group has shown synergy between oncolytic adenovirus and CD47 blockade in B16-F10 melanoma; however, it was later showed that the pH of the tumor microenvironment limits the synergy of this combination." (PMID 41322194, 2025). "We developed 3D approaches and show that CSPG4-targeting CAR-Ms in combination with CD47 blocking antibodies efficiently inhibit melanoma spheroid growth in 3D." (PMID 40082557, 2025). "Shown here are the implications of NDV-mediated CD47 blockade in murine models of melanoma and pancreatic ductal adenocarcinoma." (PMID 41322194, 2025). "When CSPG4-targeting CAR-Ms are combined with CD47 blocking antibodies, thereby blocking a key tumor cell “don’t eat me” signal, we observe enhanced phagocytosis of melanoma cells and robust inhibition of melanoma spheroid growth in 3D." (PMID 40082557, 2025). "Melanoma-expressed CD47 interacts with SIRPα on macrophages, protecting the melanoma cells from phagocytosis." (PMID 40082557, 2025). "Similar trends were observed when NDV-GFP was used in SKMEL-28 and UACC-62 human melanomas, with peak CD47 expression occurring in a dose-dependent manner." (PMID 41322194, 2025). "This is consistent with the observed impairment of CD8 effector function in chronically LCMV-infected Cd47−/− mice or mice bearing B16 melanoma tumors." (PMID 40943300, 2025). "Several studies have confirmed that the blockade of the CD47–SIRPα pathway is capable of enhancing the anti‐PD‐L1 therapy effect in melanoma." (PMID 41354057, 2025). "Studies have demonstrated that anti-CD47 antibodies can block this immune evasion pathway, restoring macrophage-mediated phagocytosis of melanoma cells." (PMID 41280655, 2025). "For example, PDK1 promotes EMT and metastasis in nasopharyngeal carcinoma, increases CD47 expression to facilitate immune escape in melanoma, and drives proliferation and invasion in ovarian and hypopharyngeal cancers." (PMID 40971960, 2025). "Inclusion of the proximal downstream binding site (+32bp) resulted in similar differences in the NRF-1 binding affinity between malignant melanoma and low CD47 expressing cells (adult melanocytes and HepG2 cells)." (PMID 39742254, 2024).